IL10 (interleukin 10)
Diseases named in the same sentence as IL10 in open-access papers (continued):
Sharing a sentence is not in itself a finding about the gene and the disease.
tumor (continued). "IL-2 and IL-10 are a type of cell growth factor in the immune system that can regulate the cell activity of white blood cells in the immune system, promote the proliferation of Th0 cells and CTLs, and also participate in the antibody response, haematopoiesis and tumor surveillance." (PMID 35445056, 2022). "These may suggest that the association between the IL-6/IL-10 mRNA expression ratio and the degree of tumor malignancy is not a strong linear positive correlation." (PMID 36371539, 2022). "Importantly, higher levels of activated Tregs were found in MA when compared with blood, meaning that tumor-infiltrating Tregs in MA produce higher levels of IL-10, express higher levels of the activation marker CD69, and proliferate at a higher extent than circulating Tregs from the same patients." (PMID 36142615, 2022). "Furthermore, interleukin (IL)-6 and IL-10 signaling have tumor-promoting functions." (PMID 36092724, 2022). "In light of the important role of TAMs in conferring tumor progression, e.g., by neoangiogenesis, and in the release of anti-inflammatory mediators, such as IL-10, to promote tumor immune evasion, it is possible that inhibition of Fscn1 in TAMs may contribute to inhibition of tumor growth." (PMID 35681718, 2022). "Moreover, M2 macrophages exert pro-tumor function by producing cytokines, such as interleukin (IL)-10 and transforming growth factor (TGF)-β, and play an immunosuppressive effect by the expression of programmed cell death ligand (PD-L1) and PD-L2 directly inhibiting cytotoxic T cell functions." (PMID 36300110, 2022). "In tumor microenvironment, cytokines played a major role in the regulation of the cellular responses between tumor cells and immune cells, for example, TGFβ, IL-10 and IL-6 could dampen the anti-tumor response of NK cells by suppressing activity and promote subsequent tumor evasion and progression." (PMID 36126190, 2022). "Therefore, the depletion by IL‐10+ and IL‐35+ Tregs may abrogate tumor‐immune evasive and resistance to immunotherapy of tumor cells." (PMID 35474948, 2022). "However, the increased expression of IL-10 in EGC may be due to the secretion by cancer cells themselves or the product of anti-tumor immune effect." (PMID 36185234, 2022). "Furthermore, scientists observed a higher amount of M2-associated mRNAs for e.g., IL-10, Arg-1, and TGFβ and the reduction of M1-associated mRNAs such as TNF-α, IL-6, and IL-12 in tumor-associated macrophages from EC specimens, in comparison to macrophages obtained from healthy specimens." (PMID 35563789, 2022). "Taken Tumor Associated Macrophage (TAM) as an example, the expression of TP73 was significantly positively correlated with a surface marker of TAM—chemokine factor CCL2 (r =0.148, P < 0.001), and another surface marker of TAM—cytokine IL10 (r =0.134, P = 0.003)." (PMID 35756491, 2022). "However, TAM-derived CCL-17, CCL-22, TGF-β, IL-10, arginase 1, and galectin-3 can significantly reduce tumor growth and metastatic sites, but the specific mechanism remains unclear." (PMID 35740975, 2022). "In addition, increased levels of IL10+ myeloid cells (e.g., neutrophils or myeloid-derived suppressor cells), as well as lowered anti-tumor M1 TAMs from tumor tissues in IP6K1 KO mice, appear to be another major contributing factor to avoid immune surveillance." (PMID 35308129, 2022). "Tumor-associated macrophages (TAMs) can secrete IL-2, IFN, and IL-12 to kill tumor cells, but they can also secrete a variety of angiogenic factors and cytokines to promote the growth of tumor cells and IL-10 to inhibit the antitumor response of cytotoxic T cells." (PMID 36230816, 2022). "Importantly, IL-10+ B cells in the tumor were increased in patients at more advanced tumor stages." (PMID 36618354, 2022).
tumor (continued). "Breg cells could produce TGF-β, IL-10, and IL-35, facilitate Treg polarization and help M2 macrophages and myeloid-derived suppressor cells (MDSCs), leading to disturbing tumor antigen presentation and promoting tumor proliferation." (PMID 36246629, 2022). "Current findings may be explained by a Treg subset of CD4+ T cells having cycled from cancer tissue into blood; alternatively, elevated levels of circulating cytokines such as IL-6, IL-10, and TGFβ may explain the tumor-suppressive profile in these blood samples." (PMID 35158758, 2022). "On the other hand, the M2 phenotype secretes cytokines such as IL-4, IL-13, IL-10, vitamin D3, and glucocorticoids, which leads to weakening of the antitumor activity and an enhancement of the ability to support angiogenesis and tissue remodeling, which is beneficial for tumor growth and invasion." (PMID 36611344, 2022). "Previously, it was shown that also celecoxib may modulate the balance between Th1 cytokines and Th2 cytokines by increasing Th1 cytokine IL-12 and reducing Th2 cytokine IL-10, although its effect on cytokine production was most evidently seen in combination with tumor lysate." (PMID 36227963, 2022). "Moreover, evidence indicates that tumor-derived TGF-β-induced overexpression of IL-10 may drive the shift in the Th1/Th2 balance toward a Th2 response and inhibit the Th1 response." (PMID 35177742, 2022). "However, radiation induces the release of myeloid-derived suppressor cells (MDSCs), M2-like tumor-associated macrophages (M2-like TAMs), T-regulatory cells (Tregs), N2 neutrophils, and immunosuppressive cytokines (TGF-β, IL-10) to promote the immunosuppressive microenvironment." (PMID 35198442, 2022). "In addition, tumor cells alter infiltrating immune cells by secreting and releasing immunosuppressive substances such as transforming growth factor, interleukin-2, interleukin-10, and vascular endothelial growth factor into the microenvironment, which impede their antitumor activities." (PMID 36275664, 2022). "However, no clinical association between the expression levels of IL-10 in tumor tissues and the prognosis of GC has been reported yet." (PMID 36371539, 2022). "As a consequence of these immunophenotypic changes in the tumour – and as appraised in Determinant 4 – there is a shift in the cytokine milieu that corresponds with reductions to immunosuppressive cytokines including IL-10 and TGF-β, which favours effector competency." (PMID 35359426, 2022). "Similarly, the INHBA+ macrophage subset co-expressed pro-tumorigenic molecules such as IL6, TGFβ, TIMP1, CCL20, CXCL1, and IL10, highlighting the highly plastic and complex nature of tumor-infiltrating myeloid cells in vivo, consistent with recent similar studies in other solid tumors." (PMID 36439171, 2022). "Thus, IL-10 can facilitate tumor escape by contributing to an immunosuppressive environment." (PMID 35784354, 2022). "Indeed, MDSCs and TAMs emit IL10 and TGF-β, while tumor-associated neutrophils (TANs), TAMs, and CAFs secrete CCL2 attracting and expanding the population of Tregs inside the tumor." (PMID 35392957, 2022). "Moreover, suppression of IL-10 cytokine by incorporating anti-IL-10 mAb improved the outcome of vaccination, which may be due to a decline in IL-10-mediated tumor invasion, as well as an increase in the proliferation of effective CTLs at the tumor site." (PMID 35752792, 2022). "Tregs may secrete IL-10, which is conventionally thought to contribute to immune suppression in the tumor microenvironment; however, it has also been identified as a factor that limits tumor growth." (PMID 36428581, 2022). "Moreover, it was reported that IL-4 and IL-10 have a direct anti-proliferative effect on some tumor cells including breast carcinomas,which may be because of their ability to increase the host antitumor response." (PMID 35974992, 2022).
tumor (continued). "Since CD4+ Th2 cells and Th2 cytokines such as interleukin-4 (IL-4), IL-5, IL-6, IL10 and IL13 were thought to be associated with immunosuppressive contexture and tumor-promoting effects, we believed that LMNB1 could be considered as a biomarker of immunosuppressive microenvironment." (PMID 35241075, 2022). "Current studies revealed that radiotherapy caused immunosuppressive effects in the tumor microenvironment due to the attraction of immunosuppressive cells such as regulatory T cells (Tregs) as well as because of the release of immunosuppressive cytokines (TGF-β and IL-10) and chemokines." (PMID 35663389, 2022). "In addition, anti-tumor immune responses may be further reduced by local production of immunosuppressive cytokines, including IL-10 and TGF-β, by tumor cells or associated stroma." (PMID 35740435, 2022). "In addition to the type 2T-helper cells, IL-10 is also produced by multiple other cell types, including monocytes, B cells, dendritic cells, keratinocytes, and tumor cells." (PMID 34152493, 2022). "In addition, IL-10, an immunosuppressive cytokine in the tumor microenvironment, was significantly increased in mice treated with 50 mW micro-LED than in those treated with 25 mW micro-LED, showing adverse effects by inflammatory responses owing to excessively high light intensity." (PMID 36258234, 2022). "For example, many miRNAs involved in the production of IL-10 and the expression of PD-L1 in TAMs exert immunosuppressive effects in an epigenetic manner, helping to identify new therapeutic targets and providing a research reference for improving tumor sensitivity to immune responses." (PMID 36131942, 2022). "In addition, anti-VEGFRs suppress the generation of Tregs, tumor-associated macrophages, and myeloid-derived suppressor cells at the tumor site and abrogate the expression of immunosuppressive cytokines such as TGF-β and IL-10." (PMID 36212444, 2022). "Furthermore, RNA-seq analysis showed that tumor-associated signaling pathways were not induced in IL10-MSCs." (PMID 35300585, 2022). "Potentially, targeting IL-10 and metabolic regulation in the tumor microenvironment may be of help." (PMID 35875098, 2022). "Luminex-based multi-cytokine analysis in the peripheral blood of tumor-bearing mice on day 35 demonstrated elevated levels of inflammatory cytokines (IFNγ, IL-1β, TNFα and Il-17) in the HS diet cohort, while there were elevated anti-inflammatory IL-10 blood levels in the LS diet cohort." (PMID 35741331, 2022). "Therefore, it is possible that IL-10 expression by tumor cells may also be a driver of poor outcomes in TNBC, and this may be independent of IgG4 + B cells." (PMID 35255925, 2022). "However, significant levels of IL-10 were found when tumor cells were cocultured with MNCs." (PMID 35955576, 2022). "Our findings are in line with previous studies and evidence shows that LEXs can promote tumour cells escape from immune system by impairing the antitumor role of T immune cells through the development of different biological proteins such as TGFβ or IL‐10 on exosomes." (PMID 35822529, 2022). "Hence, we proposed that immune-related microRNAs may be a biomarker for the immunosuppressive tumor microenvironment through modulating IL-10 or IFN-γ-mediated signaling pathway." (PMID 35675033, 2022). "Moreover, M2 ones produce the anti-inflammatory cytokine IL-10 to promote tumor development." (PMID 35210436, 2022). "Additionally, I found that IL-10 was directly toxic to tumor cells in vitro." (PMID 33912464, 2021). "However, other studies have shown tumour regression in murine models following IL-10 secretion." (PMID 34944729, 2021). "In line with these rodent experiments, administration of pegylated recombinant IL-10 (20 μg/kg) to human cancer patients induces systemic immune activation as reflected by elevations in various pro-inflammatory cytokines and expansion of both systemic and tumour-resident CD8+ T cells." (PMID 34234779, 2021).
tumor (continued). "Moreover, in vivo findings showed that metformin effectively delayed tumor growth by causing a shift from oxidative phosphorylation (OXPHOS) to glycolysis, which then decreased the Treg expression of interleukin-10 (IL-10) and cytotoxic T lymphocyte antigen-4 (CTLA-4)." (PMID 33467127, 2021). "Our results showed that patients with invasive NFPAs had higher IL-10 expression both in peripheral blood and tumor tissue than those with noninvasive NFPAs, which indicates that IL-10 may play a vital role in the development of NFPAs and present a useful biomarker for diagnosis of invasive NFPAs." (PMID 34257554, 2021). "Furthermore, HCC patients showed a decrease in proinflammatory cytokines, such as tumor necrosis factor-α (TNF-α), interferon-γ (IFN-γ), interleukin (IL)-1, and an increase in immunosuppressive cytokines (IL-4, IL-5, IL-8, and IL-10) in the tumor microenvironment, resulting in a poor prognosis." (PMID 34830949, 2021). "Sinha and Ostrand-Rosenberg reported that administration of WFA in tumor-bearing mice with 4T1 cells significantly reduces the tumor burden, decreases the number of MDSCs and reactive oxygen species (ROS), and suppresses the protumor cytokine IL-10 by the MDSCs and macrophages." (PMID 34485538, 2021). "Numerous inflammatory mediators such as TNF-α, IL-6, IL-10, IL-23, and transforming growth factor-β (TGF-β) were found to be associated with carcinogenesis and the development of CRC and their effects include pro-tumor, anti-tumor, and double-edge effects in CRC pathogenesis." (PMID 33578830, 2021). "In addition, IL-10 plays a vital role in tumor metastasis and facilitates tumor cell proliferation." (PMID 34068008, 2021). "Tumor progression may be caused by Th1/Th2 mixed reaction or Th2 dominant response, relying on TGF-β and IL-10 to transform Th1 cells into Th2 cells to reverse the anti-tumor effects of CD8+ cytotoxic T cells and CD4+ Th1 cells, which is thought to be a tumor immune escape mechanism." (PMID 34625124, 2021). "Pro-inflammatory cytokines can induce cell survival, proliferation, migration and angiogenesis, while simultaneously a tumor environment is established which protects the tumor from the host’s immune response and surveillance by the release of immunoregulatory cytokines such as IL-10." (PMID 34654395, 2021). "However, this signaling axis could also modulate cancer cell ability to grow, proliferate, invade, and metastases through IL-10 secretion as well as recruit Treg cells and myeloid-derived immunosuppressive cells to the tumor microenvironment." (PMID 33301062, 2021). "However, it is not only lymphocytes that infiltrate the TME, but other immune cells, such as tumor-associated macrophage (TAM), CD19+IL-10+ B cells (regulatory B cells), and MDSCs, can also have immunosuppressive activity in PC, resulting in tumor invasion and progression." (PMID 34868907, 2021). "This could be assigned to the action of IL-10, which was primarily produced by the tumor cells." (PMID 33141285, 2021). "Having shown CAFs actively promote the development of key phenotypic characteristics of exhausted tumor infiltrating lymphocytes and production of the immunosuppressive cytokine IL-10 we sought to identify factors produced by CAFs which might drive these changes." (PMID 34290905, 2021). "First, coculture with tumor cells inhibited the expression of M1-related genes encoding IL-6, TNF-α, and IL-1β and increased the expression of M2-related genes encoding CD163, Arg1, IL-10, TGF-β, and VEGFA, as well as expression of TNF-α and CD163 at protein level." (PMID 34093857, 2021). "This network is made up of myeloid-derived suppressor cells (MDSCs), such as immature dendritic cells, and of tumor-derived soluble factors, such as vascular endothelial growth factor, which induces the expression of regulatory T cells and immunosuppressive cytokines, such as interleukin 10 (IL-10)." (PMID 33672204, 2021).
tumor (continued). "Hence, careful selection of target cells, inhibition of IL-10 signaling at the time of immunization, and activation of IL-10 signaling at the tumor site could lead to a better cancer therapy outcome." (PMID 33628584, 2021). "In addition, TAMs expressed higher levels of IL-10 in tumor compared with non-tumor liver tissue." (PMID 35008212, 2021). "Therefore, IL-10 in 5 μg/injection would be combined with Ad-hTERT to treat the tumor-bearing mice." (PMID 33717103, 2021). "Encouraged by the results that QD-Cat-RGD could relieve hypoxic condition and reduce the infiltration of immunosuppressive cells in TME which could hinder antitumor immunity mediated by cytotoxic T cells, we tested the changes of Tregs, M2-like macrophages, and IL-10 in the TME of distant tumor." (PMID 34887404, 2021). "The local expression of IL-10 may promote tumor progression through the immunosuppression." (PMID 34079469, 2021). "Thus, the role of IL-10 signaling tumor immunotherapy remains somewhat ambiguous." (PMID 33628584, 2021). "The immune-H phenotype may be involved in immunosuppressive activities, including immunosuppressive checkpoints, expression of tumor-supportive macrophage chemotactic and polarizing molecules and immune-suppressive pathway signaling (the IL-10 signaling pathway)." (PMID 34220791, 2021). "Besides, IL-10 has been proven to play a role in anti-tumor T cells." (PMID 34717710, 2021). "However, the role of IL-10 in tumor development is controversial." (PMID 33717103, 2021). "In addition, tumor exosomes were also reported to contain notable amounts of IL-10." (PMID 34078376, 2021). "For this reason, anti-IL-10 therapies may improve the outcome of tumor therapy in the future." (PMID 34204596, 2021). "In addition, activated FcγRIIlow/– B cells from HCC tumor may also suppress host anti-tumor immune response via IL-10 signals." (PMID 33763117, 2021). "Thus, my results suggest that IL-10 was selectively toxic to tumor cell lines." (PMID 33912464, 2021). "IL-10 produced by TAMs can inhibit the function of antigen-presenting cells and then block the function of T cell effects, such as cytotoxicity, to inactivate the anti-tumor response, which leads to the downregulation of circRNAs related to the tumor response, thus promoting tumor growth." (PMID 34926295, 2021). "On the other hand, some studies suggest that IL-10 may have a tumor-supporting role." (PMID 34832887, 2021). "Moreover, during anti-tumor immunotherapy, it has been shown that USP7 inhibition causes PD-L1 increased level and IL-10 downregulation by attenuating Treg function, which may contribute to enhancing the therapeutic effect of PD-L1 treatment." (PMID 34869041, 2021). "However, IL-10 has been shown to have anti-tumor properties." (PMID 34034721, 2021). "The secreted TGF-β and IL-10 could promote Treg migration into the tumor microenvironment." (PMID 35201458, 2021). "In this study, we hypothesized that the HMC3 cells, upon stimulation with anti-inflammatory cytokines (IL-4, IL-13, IL-10, TGFβ, CCL2) released from cancer cells, will show an increased expression of immuno-suppressive and tumor-supportive proteins and associated pathways." (PMID 34566949, 2021). "Moreover, they found that XCR1 alone, or with IL10, could be a potential key regulator of the tumor microenvironment, which could also represent corroborative evidence for our speculation concerning XCR1’s involvement in ccRCC." (PMID 33377624, 2021). "However, only vvDD-IL-23 treatment significantly elevated IL-10 mRNA levels in the tumor at day 9, suggesting that IL-10 might mediate the vvDD-IL-23 induced viral persistence in tumor." (PMID 34093846, 2021). "It is known that Bregs reduce cellular responses and promote tumor growth and metastases due to the Treg cells’ generation and suppression of effector T cells and NK cells’ responses when the antitumor effect of T cells is simultaneously suppressed by IL-10 produced by the B10 cells." (PMID 33669402, 2021).